BCL2 (BCL2 apoptosis regulator)
Diseases named in the same sentence as BCL2 in open-access papers (continued):
Sharing a sentence is not in itself a finding about the gene and the disease.
breast carcinoma (continued). "METTL3 was found to be upregulated in breast cancer tissues and cells, where it promoted 6mA modification of the 3′ UTR of B-cell/lymphoma 2 (BCL-2) mRNA." (PMID 36673448, 2023). "Several studies have revealed that TAMs induce tumor chemoresistance through various mechanisms, and mammary tumors reduce the therapeutic response to anti-cancer drugs through mechanisms, such as IL-10/STAT3/Bcl2 signaling." (PMID 37369757, 2023). "MDM2 ligase coupled with inhibitors of the targets BCL2, BRD4, CDK9, PLK1 and MCL1 in stomach tumor, and MDM2 with PIK3C3 inhibitors in breast cancer, seems to be the best therapeutic strategy." (PMID 35249548, 2022). "Administration of Bcl-2 antagonist, sabutoclax, concurrently suppresses IL-6/STAT3 signaling to resensitize chemoresistant breast cancer cells to chemotherapeutic agents." (PMID 35371975, 2022). "Further, we analyzed protein and mRNA expressions of BCL-2 by western blotting and qPCR for nine cancer cell lines belonging to lung (A549, NCI-H460, and NCI-H1299), cervical (HeLa), colon (HCT-116), and breast cancers (BT474, ZR-75, MCF7, and MDA-MB-231)." (PMID 36358660, 2022). "This modulatory effect of NPS-2143 treatment can be at least attributed to its effects on the major altered signaling pathways in breast cancer such as p-ERK1/2, integrin β1 and Bcl-2, which are all often altered in breast cancer." (PMID 35620345, 2022). "Our data showed that the combination of microwave hyperthermia and lobaplatin synergistically suppressed the anti-apoptotic Bcl-2 and IAP family of proteins in breast cancer cells." (PMID 34282830, 2022). "Anti-estrogens and other agents used in ER+ breast cancer treatment such as PI3K/mTOR inhibitors and chemotherapeutics have been reported to upregulate Bcl-2 proteins, priming the cell for BH3 mimetic activity." (PMID 35053443, 2022). "In breast cancer cells, HDAC1 can induce proliferation through the upregulation of Snail/IL-8 signals, and IL-8 can suppress the apoptosis of breast cancer MCF-7 cells by down-regulating caspase-3 and up-regulating Bcl-2." (PMID 35053925, 2022). "The AUC of other breast cancer makers are as follows: ESR1 0.572 (p value 3.8 × 10−3), PGR 0.7 (p value 8.6 × 10−5), BCL2 0.577 (p value 1.3 × 10−3), SCUBE2 0.609 (p value 1.5 × 10−5)." (PMID 37304463, 2022). "Targets including BCL2, CDK4 and MCL1 were highly expressed in all tumors; MCL1 was significantly increased in breast cancer and lung adenocarcinoma and CDK4 in colon adenocarcinoma." (PMID 35249548, 2022). "Chrysophanol triggers mitochondrial-mediated apoptosis via the upregulation of the Bax/Bcl-2 ratio and is accompanied by cleavage of caspase-3 and PARP activation in optic nerve meningioma, choriocarcinoma, and breast cancer." (PMID 36676666, 2022). "Mechanistic analysis indicated that MY11 suppressed the expression of Bcl-2 and Cyclin D1 and induced the expression of PUMA, Bax, p21 and P-p65 in breast cancer cells in vitro and in vivo." (PMID 35759135, 2022).
breast carcinoma (continued). "In breast cancer, CUDC-907 enhances TRAIL-induced apoptosis through the upregulation of cell survival proteins, including XIAP, Bcl-xL, and Bcl-2." (PMID 35205815, 2022). "The Luminal B2 subtype of HER2-positive breast cancer, which overexpressed GATA3, BCL2, and ESR1 genes, was found to account for roughly half of all HER2-positive breast cancer subtypes." (PMID 36034650, 2022). "For example, depletion of METTL3 leads to an increase in the rate of apoptosis by reducing the translation of MYC, BCL2 and PTEN in leukemia cells or by BCL2 translation reduction in breast cancer cells." (PMID 36497162, 2022). "In breast cancer, GACAT3 promotes cell proliferation by reducing the levels of caspase 9 and upregulating the expression of Bcl-2 in MCF-7 cells." (PMID 35127682, 2022). "CCL28 promotes breast cancer cell proliferation and metastasis through activation of the MAPK signaling pathway, upregulation of antiapoptotic protein Bcl-2, and inhibition of cell adhesion protein β-catenin." (PMID 35463082, 2022). "In the first place, combination therapy induced 4T1 and MDA-MB-231 breast cancer cell apoptosis via the activation of the JNK signaling pathway, inhibiting the AKT/mTOR signaling pathway and down-regulating the Bcl-2 and IAP family." (PMID 34282830, 2022). "Rottlerin treatment results in BCL2- and BECN1-independent autophagic death in apoptosis-resistant breast cancer MCF-7 cells." (PMID 36497321, 2022). "When the Bax/Bcl-2 ratio is elevated and PrPC is down-regulated, apoptosis mediated by TRAIL is more likely to occur in adriamycin resilient human breast cancer cells." (PMID 36359353, 2022). "Similar results were also observed in the study on MCF-7 breast cancer cell line that the regulation of VD3 on apoptosis was BAX and BCL2 depended." (PMID 36159807, 2022). "In breast cancer, GACAT3 promotes cell apoptosis by downregulating caspases 3 and 9 as well as by upregulating BAX and Bcl-2 via miR-497 in MCF-7 cells." (PMID 35127682, 2022). "Apoptosis mechanism mediated by a decrease in Bcl-2 expression and an increase in caspase-3 and caspase-9 expression in MCF7 breast cancer cells." (PMID 35208993, 2022). "Alternatively, BP1 transcriptionally activates bcl-2 and inhibits tumor necrosis factor (TNF)-α-induced cell death in MCF7 breast cancer cells." (PMID 35883028, 2022). "Both arsenic compounds upregulate expression levels of antiapoptotic genes BCL2 and BCL2L1 and downregulate expression levels of proapoptotic genes CASP8 and CASP9, promoting apoptosis in breast cancer cells." (PMID 36619302, 2022). "The treatment of drug-resistant MDA-MB-231 breast cancer cells with tangeretin induced apoptosis by increasing BAX, caspase-3, and -8 and decreasing Bcl-2." (PMID 36142874, 2022). "Therefore, when the expression of BCL-2 is reduced, breast cancer may be induced." (PMID 36313628, 2022). "Exercise is also reported to downregulate miR-21 and the anti-apoptotic protein Bcl-2 and increase the expression levels of the tumor suppressor PDCD4 in an animal model of breast cancer." (PMID 35945569, 2022). "Another eight ARGs (BCL2, BIRC5, EIF4EBP1, ERO1L, FOS, GAPDH, ITPR1, and VEGFA) were explored, and the author found that these genes not only were significantly associated with overall survival but also could predict distant metastasis-free survival in breast cancer." (PMID 34869345, 2021). "In a study investigating the influence of DOX on apoptosis in breast cancer cell lines, DOX upregulated Bax, caspase-8 and caspase-3 expressions while downregulating the anti-apoptotic Bcl2 and Bcl-xL levels." (PMID 33750916, 2021).
breast carcinoma (continued). "Nobiletin induced cell death in human breast cancer MCF-7 cells by modulating the expression of Bax and Bcl-2 proteins." (PMID 34768743, 2021). "Combined inhibition of BCL-2 and BCL-xL with ABT-263 had limited efficacy on breast cancer owing to high expression of MCL-1, while A-1210477 or VU661013 in combination ABT-263 has a synergistic effect." (PMID 33883020, 2021). "TQ treatment for 24 hours reduced the mRNA level expression of the anti-apoptotic B-cell lymphoma 2 (Bcl-2) gene in MDA-MB-231 and MCF-7 breast cancer cells, according to real-time qRT-PCR analysis." (PMID 34582654, 2021). "As a result, increased expression of BCL2 indicated favorable OS and RFS and high expression of MYC had good OS but poor RFS in breast cancer." (PMID 34828282, 2021). "Examples of immune targets under investigation for the treatment of specific breast cancer subtypes include B7-H3, LAG3 and CTLA4; there is also interest in assessing the role of Bcl-2 inhibition in selected patients with breast cancer." (PMID 34838031, 2021). "Together, these results support clinical evaluation of BCL-2 inhibitors within the context of lapatinib and the treatment of HER2+/ER+ breast cancers." (PMID 33951110, 2021). "Many Bcl-2 family members, including Bcl-2, Bax, Bak, and Bcl-xL are known to impact PTX sensitivity in breast cancer." (PMID 34370741, 2021). "In human breast cancer cell MCF7, MG132 treatment up-regulated the expression of GRP-78, CHOP, Bax and Caspase-3, and down-regulated the expression of Bcl-2, resulting in increased apoptosis." (PMID 34809635, 2021). "In conclusion, this study concludes that soy isoflavone Daidzein induces cell death in breast cancer cells MCF-7 mediated by over-expression of pro-apoptotic protein Bax and lowering the expression of anti-apoptotic marker Bcl2." (PMID 33639680, 2021). "It has been demonstrated that silybin stimulated under-expression of Bcl-2 and overexpression of Bax and Casp-8, Casp-9, and BID in MCF-7 breast cancer cells." (PMID 34094034, 2021). "There was higher expression of IL6, MCP1, BCL2, luminal cytokeratins, MUC1, BRCA1, BRCA2, CEA and CA 15-3 in older women with primary breast cancer compared to younger women." (PMID 34165702, 2021). "The viability of the breast cancer cell line MCF-7 and MDA-MB-231 upon exposure of siRNA targeting three anti-apoptotic genes, namely, Mcl-1, Bcl-2, and survivin, was examined by MTT assay." (PMID 33919902, 2021). "The PGR (progesterone receptor), BCL2 Apoptosis Regulator and SCUBE2 (Signal Peptide, CUB Domain And EGF Like Domain Containing 2) are known to be a favorable prognostic marker on breast cancer recurrence." (PMID 34462515, 2021). "Reducing NRG1 expression by small interfering RNA increased cell proliferation in both normal and human breast cancer cells, whereas expression of NRG1 induced apoptosis via the downregulation of the BCL2 apoptosis regulator." (PMID 34068503, 2021). "Diels (ASP) induces breast cancer cells apoptosis by influencing PARP, Bax, Bcl-2, Bcl-xL, and Apaf-1 protein expression in human breast T47D and Hs578T cells through caspase-3 signaling pathways." (PMID 33807287, 2021). "cugWT1 is highly expressed in breast cancer cells, which can mediate tumor cell transformation and up-regulate c-MYC, BCL2, and EGFR expression; silencing it leads to decreased anchorage-independent growth and proliferation of breast cancer cells." (PMID 32210734, 2020).
breast carcinoma (continued). "In breast cancer, miR-21 and miR-125b target programmed cell death 4 (PDCD4) and BCL2-antagonist/killer 1 (BAK1), respectively, eventually aggravating paclitaxel resistance." (PMID 33066509, 2020). "Specifically, diosgenin decreased the expression of NF-kappaB, Bcl-2, cyclin D1, Cdk-2, Cdk-4, survivin, and XIAP in breast cancer cells." (PMID 32626765, 2020). "High levels of IL-10 have been reported to be responsible for drug resistance to breast cancer, in which the blockade of this cytokine resulted in diminished STAT3 activation and a decrease in Bcl-2 mRNA expression, and consequently the induction of apoptosis." (PMID 32244885, 2020). "Despite the interaction between DSCAM-AS1 and hnRNPL at BCL2, 3′UTR deserves further experimental validations, and DSCAM-AS1 represents a good candidate to regulate this process in luminal breast cancer cells." (PMID 32503257, 2020). "In other studies, fucoidan decreased the expression of anti-apoptotic signals including Bcl-2, Bcl-XL, and MCL-1 in breast cancer." (PMID 31936539, 2020). "For both TNBC cells, AG8 treatment increased the Bax/Bcl-2 ratio significantly, suggesting that the Bcl-2 family of proteins is involved in AG8-induced apoptosis in breast cancer cells." (PMID 33123316, 2020). "Such as the combination of paclitaxel targeted BCL2 and lapatinib targeted EGFR was reported to be effective for HER2 + breast cancer in the clinical trial phase 3." (PMID 32523951, 2020). "Apoptotic activity (increased Bax/Bcl-2 ratio) and anti-proliferative potential against MCF-7 breast cancer cells of silver nanoparticles synthesized from aqueous extract of sumac was described in another recent study." (PMID 33375383, 2020). "The proteome-level data obtained by us provide a stepwise clinical procedure in YARS-positive breast cancer patients, which involves an initial screening test for YARS, followed by treatment of YARS-positive breast cancer patients with SM and BCL2 inhibitors." (PMID 33239070, 2020). "Recently, on the basis of the GEO database, Gu and his colleagues constructed an ARG model consisting of eight genes (BCL2, BIRC5, EIF4EBP1, ERO1L, FOS, GAPDH, ITPR1, and VEGFA), which can be used as an independent prognostic indicator of breast cancer." (PMID 32649310, 2020). "STAT3 signaling pathway plays a crucial role in proliferation (Bcl-2, Survivin), angiogenesis (HIF1α, VEGF), and epithelial-mesenchymal transition (Vimentin, MMP-9) in breast cancer cells and has been validated as a drug target for cancer therapy." (PMID 31948057, 2020). "To test this possibility, we further examined the correlation between the expressions of EMT genes, Bcl-2, and JNK target gene JUN in both patient tumors and CTCs and the survival of breast cancer patients." (PMID 33143160, 2020). "In addition, injecting UD extract intraperitoneally into a mouse model with breast cancer was able to elicit intrinsic apoptotic pathway activation through increased expression of the pro-apoptotic caspase-3 and downregulation of the anti-apoptotic Bcl-2 protein." (PMID 32872275, 2020). "Quantification of RNA expression of the BCL-2 family proteins (BCL-2, MCL-1 and BCL-xL) in breast cancer cell lines and primary patient samples found higher MCL-1 transcripts compared to BCL-2 and BCL-xL." (PMID 33308268, 2020).
breast carcinoma (continued). "Consistently, using synthetic lethality screen, Marusyk and colleagues identify BCL-2/BCL-xL inhibitors (ABT-737 and ABT-263) as candidates to overcome CAF-induced resistance to lapatinib in breast cancers." (PMID 33080792, 2020). "Combination treatment with necroptosis-inducing small molecules, including a SMAC mimetic (LCL161) and a pan-BCL2 inhibitor (ABT-263), showed therapeutic efficacy in YARS-overexpressing breast cancer cells." (PMID 33239070, 2020). "The drug was also able to significantly increase the nuclear condensation, and modulated the expression of certain genes involved in breast cancer, such as caspases 3, and 9, BAK-1, C-MYC, BCL2L1, BCL-10, and BCL-2." (PMID 32746451, 2020). "MET treatment also increased the proportion of apoptotic drug‐sensitive and drug‐resistant breast cancer cells, induced cleavage of caspase‐3, increased BAX expression and decreased BCL2 expression." (PMID 32281270, 2020). "Meanwhile, the OA derivative SZC015 induced a mitochondrial apoptotic pathway in human breast cancer cells by activating cleaved caspase-3, caspase-9, cytosolic Cyt C, and PARP and increasing the Bax/Bcl-2 ratio." (PMID 32998255, 2020). "Decreased level of Bcl-2 and the increased levels of Bax and Caspase-3 were also observed, suggesting that knock down of OLA1 also promoted the sensitivity of breast cancer cells with intrinsic resistance to chemotherapy." (PMID 32528278, 2020). "The current findings showed that Ki-67 and BCL-2 biomarkers were highly expressed in stage III and/or IV and grade 2 and/or grade 3 of breast carcinoma." (PMID 31289309, 2019). "Ectopic upregulation of miR-34a expression led to partial MDR reversal, reduction of target genes Ccnd1, Notch1 and BCL2 expression and increased apoptotic rates in MDR breast cancer cells." (PMID 35582270, 2019). "This is supported by its co-expression with antiapoptotic proteins; BCl2, AKT1 and NF Kappa-B in residual breast carcinoma cells and very low proliferating index and apoptotic bodies in residual tumors." (PMID 30744593, 2019). "Inhibition of Akt phosphorylation, mTOR and Bcl2 along with increased BAX expression and caspase 3 cleavage are also involved in mediating apoptosis in curcumin treated breast cancer cells." (PMID 31618928, 2019). "Others have shown that targeting the pro-survival BCL2 proteins of the BAD pathway, using the BH3 mimetic ABT-737, sensitized basal-like breast cancers to chemotherapy." (PMID 31767884, 2019). "Previous studies have demonstrated that β2-microglobulin (β2M) promotes the growth and survival of a variety of cancer cells and has different regulatory effects on the expression of Bcl-2 and HER2 in HER2− breast cancer cells." (PMID 30866857, 2019). "Mcl-1 upregulation has been determined in 28% of human breast cancer cell lines as reported by the cancer cell line encyclopedia (CCLE), whereas Bcl-2 is upregulated in 3%." (PMID 31404252, 2019). "In human breast cancer cells (MCF7 cells), 10-150 μM Res negatively regulated breast cancer cell growth via Bcl-2 and NFkB." (PMID 30779707, 2019). "Further reported CASC9 target genes were CDK4, CyclinD1 (CCND1), E-Cadherin (CDH1) and BCL2 in lung adenocarcinoma, ESCC cells, oral squamous cell carcinoma and in breast cancer." (PMID 31412811, 2019). "We demonstrate the translational potential of an AMPK and BCL-2/BCL-XL co-targeting strategy in ex vivo and in vivo models of MYC-high breast cancer." (PMID 30728358, 2019).